SHOX (SHOX homeobox)
Description:
Transcription factor that controls fundamental aspects of growth. Directly activates NPPB transcription in osteogenic cells. Preferentially binds DNA elements with the sequence 5'-TAATNNNATTA-3', possibly as a homodimer.
Synonyms: PHOG; GCFX; SS; SHOXY; SHOX1
Tractability: PROTAC: ubiquitination databases record sites on it.
Gene: Protein-coding gene on chromosome X (624,344 to 659,411, forward strand). Ensembl gene ENSG00000185960.
Subcellular location: Nucleus
Subcellular location (Human Protein Atlas): Nucleoplasm; Vesicles
Gene Ontology:
Molecular function: DNA-binding transcription activator activity, RNA polymerase II-specific; protein binding; sequence-specific DNA binding; sequence-specific double-stranded DNA binding; DNA-binding transcription factor activity, RNA polymerase II-specific; DNA binding
Biological process: positive regulation of transcription by RNA polymerase II; regulation of transcription by RNA polymerase II; skeletal system development; regulation of DNA-templated transcription
Cellular component: nucleoplasm; nucleus; chromatin
Homologues: Orthologues: chimpanzee SHOX (100% identical), macaque SHOX (99% identical), dog SHOX (96% identical), tropical clawed frog shox (87% identical), zebrafish shox (85% identical). Paralogues in human: SHOX2 (71% identical), ARX (34% identical), OTP (26% identical), VSX2 (26% identical), UNCX (26% identical), ALX4 (25% identical), PITX3 (25% identical), RAX (25% identical), PAX7 (25% identical), PRRX2 (25% identical), PAX3 (24% identical), DMBX1 (24% identical), and 38 more.
Diseases named in the same sentence as SHOX in open-access papers:
SHOX is named in the same sentence as 69 diseases in open-access papers, as found by Europe PMC text mining. Sharing a sentence is not in itself a finding about the gene and the disease. The quoted sentences say what the papers report.
Leri-Weill dyschondrosteosis (44 papers, 2007 to 2026). Leri-Weill dyschondrosteosis (LWD) is a skeletal dysplasia marked by disproportionate short stature and the characteristic Madelung wrist deformity. "The foetus had short limbs due to SHOX haploinsufficiency associated with Leri-Weill dyschondrosteosis (LWD)." (PMID 38129867, 2023). "SHOX deficiency causes a spectrum of clinical phenotypes related to skeletal dysplasia and short stature, including Léri-Weill dyschondrosteosis, Langer mesomelic dysplasia, Turner syndrome, and idiopathic short stature." (PMID 34122528, 2021). "SHOX haploinsufficiency causes 70–90% of Léri-Weill dyschondrosteosis (LWD) and 2–10% of idiopathic short stature (ISS)." (PMID 32647378, 2021). "Haploinsufficiency of the SHOX gene is associated with short stature and diverse skeletal anomalies, such as Leri-Weill dyschondrosteosis (LWD)." (PMID 33344636, 2020). "SHOX mutations have previously been described as causes of Léri-Weill dyschondrosteosis (LWD), Langer mesomelic dysplasia (LMD), and idiopathic short stature." (PMID 33240610, 2020). "A deletion of SHOX is one of the known causes of Léri–Weill dyschondrosteosis and isolated short stature, while three copies of SHOX in cases with triple sex chromosome constitution are responsible for tall stature." (PMID 30530863, 2019). "Haploinsufficiency of the human SHOX gene causes Léri-Weill dyschondrosteosis (LWD), characterized by shortening of the middle segments of the limbs and Madelung deformity of the wrist." (PMID 30250174, 2018). "SHOX deficiency is also the primary cause of short stature in most patients with Leri-Weill dyschondrosteosis." (PMID 28948052, 2017). "Previously, SHOX gene deletions have been implicated in Léri-Weill dyschondrosteosis (OMIM # 127300) and Langer mesomelic dysplasia (OMIM # 249700)." (PMID 27034718, 2016). "SHOX gene mutations or haploinsufficiency cause a wide range of phenotypes such as Leri Weill dyschondrosteosis (LWD), Turner syndrome, and disproportionate short stature (DSS)." (PMID 24689071, 2014). "Mutations or deletions of SHOX in humans cause short stature in Turner, Langer and Leri-Weill syndrome as well as idiopathic short stature." (PMID 23028966, 2012). "The heterozygous loss of SHOX function due to deletions or mutations has been shown to cause Leri-Weill Dyschondrosteosis (LWD) while homozygous loss leads to Langer mesomelic dysplasia." (PMID 21448463, 2011). "Mutations in the SHOX gene are responsible for Leri-Weill Dyschondrosteosis, a disorder characterised by mesomelic limb shortening." (PMID 21731768, 2011). "Like ARSE, SHOX genes are involved in skeletal development: mutations and deletions in SHOX lead to Leri-Weill dyschondrosteosis and non-syndromic idiopathic short stature, and deletions cause the short stature phenotype seen in Turner syndrome." (PMID 18842153, 2008). "In addition, previous studies have shown that skeletal abnormalities and growth disorders are associated with defects in the SHOX gene, such as Leri-Weill syndrome (LWD), Turner syndrome (TS) and idiopathic short stature (ISS)." (PMID 38281003, 2024). "Mutations of SHOX are found in patients with Léri-Weill dyschondrosteosis and Langer dysplasia." (PMID 36587229, 2022). "Regarding group 17, morphants of zebrafish shox gene also show growth retardation and decreased vertebral and craniofacial ossification, which resembles symptoms shown in patients with dyschondrosteosis (Leri-Weill) or mesomelic dysplasia Langer type, diseases caused by SHOX mutations." (PMID 34490030, 2021). "Alterations in SHOX expression impairs human growth and causes a spectrum of clinical phenotypes related to skeletal dysplasia and short stature including Léri-Weill dyschondrosteosis, Langer mesomelic dysplasia, Turner syndrome, and idiopathic short and tall stature." (PMID 34122528, 2021).
Leri-Weill dyschondrosteosis (continued). "Mutations or deletions of SHOX have been identified as the primary cause of several disorders characterized by reduced body height and skeletal deformities including the short stature associated with Turner Syndrome, Léri-Weill Dyschondrosteosis and Langer Syndrome." (PMID 23028966, 2012). "Investigations into regulatory elements around SHOX have found that deletion of conserved non-coding elements (CNEs) downstream of the SHOX gene produces a phenotype indistinguishable from patients with mutations in the SHOX coding region and so resulting in Leri-Weill Dyschondrosteosis." (PMID 21731768, 2011). "Mutations in the short stature HOX gene, SHOX have been shown to be responsible for the dominantly inherited skeletal dysplasia Leri-Weill Dyschondrosteosis (LWD)." (PMID 21731768, 2011). "Loss of function of the SHOX gene in the pseudoautosomal region of Xp (haploidy insufficiency) may contribute to short stature and skeletal characteristics in patients, and was associated with Leri-Weill dyschondrosteosis, Langer mesomelic dysplasia, and X-linked idiopathic familial short stature." (PMID 38383389, 2024). "The deletion of SHOX resulted in both girls having symptoms concordant with Leri‐Weill dyschondrosteosis (MIM# 127300)." (PMID 35842787, 2022). "SHOX gene mutations have previously been described as causes of Leri-Weill dyschondrosteosis (LWD), Langer mesomelic dysplasia (LMD), idiopathic short stature (ISS), and its haploinsufficiency is described as the cause of growth restriction in Turner syndrome (TS)." (PMID 33240610, 2020). "Using SNP array, we detected that the female proband with Leri-Weill dyschondrosteosis (LWD) carried an 857 kb deletion on Xp22.3 (encompassing SHOX enhancer) and a 5,707 kb large-fragment deletion on Xq25q26." (PMID 31781162, 2019). "Although some studies point to a correlationbetween SHOX gene deletions and short stature and Leri-Weill dyschondrosteosis, others have found some patientswith the same clinical features who had partial or fullduplications of SHOX gene." (PMID 31210441, 2019). "The deletion of the SHOX gene together with the Madelung deformity of the forearm and the short stature of the proband led to a diagnosis of Léri-Weill dyschondrosteosis (LWD)." (PMID 27588041, 2016). "The homeodomain transcription factor SHOX is involved in different human short stature syndromes (Turner syndrome, Léri-Weill dyschondrosteosis LWD [MIM 127300] and Langer mesomelic dysplasia [MIM 249700]) and isolated (idiopathic) short stature [MIM 300582]." (PMID 24887312, 2014). "Deficiency of the human short stature homeobox-containing gene (SHOX) has been identified in several disorders characterized by reduced height and skeletal anomalies such as Turner syndrome, Léri-Weill dyschondrosteosis and Langer mesomelic dysplasia as well as isolated short stature." (PMID 24887312, 2014). "Mutations and deletions in SHOX have been reported to cause short stature in patients with idiopathic short stature (ISS, OMIM #300582), Turner syndrome, dyschondrosteosis (Leri-Weill syndrome, LWD, OMIM #127300) and its more severe form Langer mesomelic dysplasia (OMIM #249700)." (PMID 21806840, 2011). "Gross deletions at the SHOX locus lead to protein insufficiency and are manifested by growth disorders such as Leri-Weill dyschondrosteosis (LWD), Langer mesomelic dysplasia (LMD), and idiopathic short stature (ISS)." (PMID 41683999, 2026). "Mutations in the SHOX gene and deletions of conserved non-coding elements (CNEs) downstream of the SHOX gene have been shown to be responsible for the dominantly inherited skeletal dysplasia Leri-Weill Dyschondrosteosis (LWD)." (PMID 21731768, 2011).
Leri-Weill dyschondrosteosis (continued). "In addition, we determined the TSCS scores for seven subjects with loss-of-function SHOX point mutations, six with SHOX haploinsufficiency (dyschondrosteosis) and one with complete absence of SHOX (an 84-year old woman with Langer mesomelic dysplasia due to compound heterozygosity)." (PMID 17517138, 2007). "Heterozygous SHOX variants leading to haploinsufficiency result in non-syndromic SHOX-deficient short stature (SS, MIM 300582) at the mild end and Leri–Weill dyschondrosteosis (LWD, MIM 127300) at the severe end of the clinical spectrum." (PMID 37107635, 2023). "Recent investigations into regulatory elements surrounding SHOX have shown that deletions of conserved non-coding elements (CNEs) downstream of the SHOX gene produce a phenotype indistinguishable from Leri-Weill Dyschondrosteosis." (PMID 21731768, 2011).
Turner syndrome (29 papers, 2008 to 2026). Turner syndrome is a chromosomal disorder associated with the complete or partial absence of an X chromosome. "Short stature homeobox-containing (SHOX)-gene haploinsufficiency causes short stature both in isolated SHOX deficiency and in Turner syndrome (TS), yet head-to-head data on growth-hormone (GH) outcomes remain scarce." (PMID 42243538, 2026). "Turner syndrome (TS), a chromosomal disorder affecting females, is commonly associated with short stature due to haploinsufficiency of the SHOX gene." (PMID 41195213, 2025). "Well-known examples have included Turner syndrome (45,X), Fragile X syndrome (Xq28), and individuals carrying mutations of the SHOX gene mapped to Xp22.1." (PMID 38031145, 2023). "By far, haploinsufficiency of the escape gene SHOX on chromosome X is convincingly linked to short stature of Turner syndrome." (PMID 36457060, 2022). "SHOX haploinsufficiency underlies the short stature of Turner syndrome patients and is associated with ISS and LWD." (PMID 36611397, 2022). "The loss of X chromosome—Turner syndrome or mosaic 45,X/46,XX or 46,XY—also leads to the heterozygous loss of SHOX in patients with short stature only or with features similar to LWD." (PMID 33240610, 2020). "The SHOX gene (short stature homeobox), located on Xp22.23, is the only X-chromosome gene that is truly linked with a phenotypic trait in Turner syndrome, i.e., short stature and skeletal growth." (PMID 32356180, 2020). "SHOX deficiency contributes to the skeletal features in Turner syndrome." (PMID 36672881, 2023). "Phenotypic variation exists among individuals with SHOX deficiency because a high-arched palate is more prevalent in Turner syndrome, whereas Madelung deformity, a short forearm and lower leg, bowing of the forearm and tibia, and muscular hypertrophy are more prevalent in Léri–Weill syndrome." (PMID 36611397, 2022). "The SHOX deficiency in Turner syndrome may explain cubitus valgus, Madelung deformity, mesomelia, disproportionate skeletal sizes, a high-arched palate, and micrognathia." (PMID 36611397, 2022). "Thus, SHOX haploinsufficiency is associated with short stature (as seen with Turner syndrome), and additional SHOX genes (as seen with sex-chromosome polyploidies such as Klinefelter syndrome, triple X syndrome, and XYY syndrome) are associated with tall stature." (PMID 28948052, 2017). "Using the rationale that girls with Turner syndrome, whose short stature is believed to be due, at least in part, to SHOX haploinsufficiency, have had good response to GH treatment, GH was later evaluated in children with isolated SHOX deficiency." (PMID 28948052, 2017). "Because the SHOX gene is located on the sex chromosomes, most women with Turner syndrome have only one copy of the gene in each cell instead of the usual two copies." (PMID 23509644, 2013). "SHOX is thought to regulate human skeletal growth, and deletions of the gene to result in short stature (as in Turner syndrome) and an extra copy in tall stature (as in sex chromosome trisomies)." (PMID 21806840, 2011). "SHOX was discovered when looking for a Turner syndrome short-stature gene in the Xp-Yp pseudoautosomal region (PAR1)." (PMID 21731768, 2011). "SHOX is thus haploinsufficient in females with 45,X Turner syndrome, accounting for approximately two-thirds of the characteristic growth deficit." (PMID 21731768, 2011). "Furthermore, SHOX haploinsufficiency is directly associated with the skeletal abnormalities observed in LWD and Turner syndrome, the latter also involving craniofacial abnormalities." (PMID 39389973, 2024). "In addition to Turner syndrome (monosomy X), the SHOX gene mapped to the pseudo-autosomal region 1 (PAR1) at Xp22 has also been associated with body height." (PMID 38031145, 2023). "Of the escape genes, SHOX, STS, KDM5C, KDM6A, UBA1, and RPS4X were associated with Turner syndrome." (PMID 36457060, 2022).
Turner syndrome (continued). "Léri-Weill dyschondrostenosis, a type of SHOX haploinsufficiency, and some instances of Turner syndrome result in a short fourth metacarpal bone and radius and ulna deformities, collectively known as Madelung deformity, which is related to premature fusion of the lesions." (PMID 36072933, 2022). "Patients with Turner syndrome (45,X) suffer from a high fracture risk and have reduced cortical bone structures and bone mineral density, but whether this is due to reduced SHOX expression is not known." (PMID 24887312, 2014). "This loss of genes is intriguing since many of them have been demonstrated to be clinically significant to humans; among these are, e.g., SHOX (SHOX homeobox) and ANOS1 (anosmin 1), responsible for the phenotypes of Turner syndrome or Kallmann syndrome, respectively." (PMID 40136496, 2025). "The mean ΔBA/ΔCA in untreated Japanese patients with Turner syndrome with no spontaneous puberty was 0.75 ± 0.63 before BA 10 years, owing to chromosome imbalance, hypogonadism, and SHOX haploinsufficiency." (PMID 36072933, 2022). "The Italian Medicines Agency (AIFA) recognizes GH therapy for a number of conditions, including but not limited GHD, SHOX haploinsufficiency, Turner syndrome, and children born small for gestational age; however, ISS is not formally included among reimbursed indications." (PMID 40723048, 2025). "Interestingly, after the association between SHOX haploinsufficiency and Turner syndrome was established, it did not take very long for the FDA to approve rhGH treatment for those children with SHOX deficiency." (PMID 34290673, 2021).
Léri-Weill dyschondrosteosis (27 papers, 2008 to 2026). "Subsequently, SHOX haploinsufficiency has been demonstrated in individuals exhibiting different phenotypes, ranging from idiopathic short stature (ISS) to Lėri-Weill dyschondrosteosis (LWD)." (PMID 31781162, 2019).
Langer mesomelic dysplasia (19 papers, 2011 to 2026). Langer mesomelic dysplasia (LMD) is characterized by severe disproportionate short stature with mesomelic and rhizomelic shortening of the upper and lower limbs. "In contrast to SHOX haploinsufficiency, total loss of SHOX due to biallelic SHOX null variants is rare and causes the severe skeletal disorder, Langer mesomelic dysplasia (LMD; MIM 249700)." (PMID 37107635, 2023). "SHOX homozygous mutations or compound heterozygous mutations cause Langer syndrome, a very rare condition with severely disproportionate short stature (mesomelic dysplasia due to the underdeveloped or absent ulna and fibula) and the Madelung deformity." (PMID 36611397, 2022). "The best-known example is SHOX, of which biallelic defects cause Langer syndrome with severe dwarfism, monoallelic defects Leri–Weill syndrome or non-syndromic short stature, and gene duplications non-syndromic tall stature." (PMID 34194391, 2021). "Therefore, the SHOX deficiency represents a complex and heterogeneous group of conditions ranging from the more severe phenotype (Langer syndrome) to milder forms (isolated short stature/isolated Madelung deformity)." (PMID 25056248, 2014). "Loss of both copies of SHOX cause Langer mesomelic Dysplasia (LMD; MIM #249700), which is a condition with extreme short stature, severe shortening or aplasia of the ulna and fibula, as well as boththickening and curvature of the radius and tibia." (PMID 30626445, 2019). "Homozygous or compound heterozygous mutations as well as biallelic deletions of SHOX and/or the enhancer regions result in a more severe phenotype, which is known as Langer Mesomelic Dysplasia (LMD; MIM #249700)." (PMID 30626445, 2019). "SHOX gene function is dosage-dependent, and the phenotypic aspects range from very short, dysmorphic stature (Langer syndrome) to Leri–Weill dyschondrosteosis (LWD) and idiopathic short stature, respectively." (PMID 36611397, 2022). "Additionally, a loss of both copies of SHOX results in the occurrence of Langer mesomelic dysplasia (LMD), which is a more severe disorder." (PMID 31781162, 2019). "SHOX mutations in humans mainly affect the bones of the zeugopod region (LWD, Langer syndrome) which is in conformity with the most prominent expression of the chicken and human SHOX gene in the middle part of the developing limb." (PMID 23028966, 2012). "In cases with SHOX deletion, the phenotype is highly variable; the moment of diagnosis may be from birth in Langer Mesomelic Dysplasia, children with SGA, or adult life when the diagnosis is established due to family gene analysis." (PMID 36611397, 2022). "Studies in human and chicken revealed specific SHOX expression in the pharyngeal arches and the early developing limbs during embryonic and fetal development, consistent with the symptoms seen in Turner and Langer syndrome as well as LWD." (PMID 21448463, 2011). "The homeobox gene SHOX is known to play a key role during limb development, and mutations or deletions lead to the limb malformations seen in LWD and Langer syndrome or to short stature without limb anomalies in patients with idiopathic short stature." (PMID 23028966, 2012). "However, obvious brain malformations or cognitive developmental delay have not been described in patients with LWD, Turner or Langer syndrome or ISS patients with SHOX haploinsufficiency." (PMID 21448463, 2011).
dwarfism (4 papers, 2021 to 2024). "Early detection of SHOX gene mutations and skeletal malformations is an important guideline for the diagnosis and management of dwarfism." (PMID 38281003, 2024). "This is the first case report of familial idiopathic dwarfism caused by mutation at the c.577G > A locus of exon 5 of SHOX gene in the world." (PMID 37832088, 2023). "The deficiency of these two genes (SHOX and HMG) would result in dwarfism." (PMID 35562825, 2022).